SOX2 (SRY-box transcription factor 2)
Diseases named in the same sentence as SOX2 in open-access papers (continued):
Sharing a sentence is not in itself a finding about the gene and the disease.
neurological disease (5 papers, 2013 to 2024). "Sox2 is now recognized as a key transcription factor that is involved in multiple neurological diseases." (PMID 23874697, 2013). "DEHP profoundly stimulated NSCs proliferation through Sox2 geneoverexpression.These results provide and opportunity for further use of the C. vulgure phytochemicals forprevention and/or treatment of neurological diseases via phytochemical mediated-proliferation of endogenous adult NSCs." (PMID 28367427, 2017). "Other identified regulators are involved in reactive gliosis, such as SOX2 which plays a role in astrocyte activation after traumatic brain injury, and STAT3 which has been widely implicated in astrocyte activation and inflammation during neurological disease, and under hypoxic/ischemic conditions." (PMID 38528608, 2024). "The study shows that proteins (SOX2, STAT1, AKT1, and CTNNB1) can be used as markers for neurological disease at the early stage of neuronal development, and they can be potential drug targets for therapeutic development." (PMID 30598663, 2018).
neurodegenerative disease (4 papers, 2014 to 2024). A disorder of the central nervous system characterized by gradual and progressive loss of neural tissue and neurologic function. "Moreover, the SOX2-encoded product SOX2ot is considered to be a potential marker of neurodegenerative diseases." (PMID 31481902, 2019).
brain diseases (3 papers, 2019 to 2024). "Among the genes annotated to SOX2-bound elements, numerous have been associated with astrogliosis and reactive astrocyte proliferation after TBI or other brain diseases, such as Nr2e1, Mmd2, Wnt7a, and Akt2." (PMID 38672150, 2024).
genetic disease (3 papers, 2011 to 2022). "Finally, we will also discuss some implications of mouse models of SOX2 function for the understanding of human genetic disease, caused by heterozygous mutations in SOX2." (PMID 35626641, 2022). "In keeping with several genetic disorders, we found that SOX2 mutations were associated with older parental age and the difference was statistically significant for mothers (p=0.05), whereas, although not statistically significant, SOX2 deletion cases had younger parents." (PMID 22171155, 2011).
hematologic cancers (2 papers, 2018 to 2021). "SORE6, an in-vitro reporter system, was designed to quantify the transcription activity of Sox2/Oct4 and identify CSL cells in non-hematologic cancers." (PMID 34287231, 2021).
peripheral neuropathy (2 papers, 2020 to 2024). A disorder affecting the peripheral nervous system. "These downregulated miRNAs likely contribute to the peripheral neuropathy observed in the PLP-cKO mice, because these miRNAs target myelin inhibitory proteins of c-Jun, Sox2 and Notch, and axonal inhibitory proteins of PTEN." (PMID 39285940, 2024). "Considering the lack of a rescue, continued Sox2 expression is not the major decisive determinant of the peripheral neuropathy in Rnf40ΔSC mice, but rather one of several contributing factors." (PMID 32672815, 2020).
endocrine tumors (1 paper, 2016). "Decreased protein expression of Sox2 was also confirmed in endocrine tumors of the pancreas and parathyroids from the Men1 KO mice by IF and western blot assays." (PMID 26871472, 2016).
head and neck tumors (1 paper, 2018). "To further assess the clinic correlation of KLF4 and SOX2, we evaluated the expression of KLF4 and SOX2 in the 500 head and neck tumors with RNA sequencing data available from TCGA." (PMID 30108202, 2018). "Moreover, we evaluated the expression of SOX2 and PIK3CA in the 520 head and neck tumors with RNA sequencing data available from TCGA." (PMID 30108202, 2018).
retinal disorder (1 paper, 2025). Any disease or disorder of the retina. "Understanding RAX2’s interactions with key developmental genes like PAX6 and SOX2 is crucial for advancing gene therapy approaches for retinal disorders." (PMID 40538981, 2025).
SOX2 also shares sentences with these, for which no sentence is quoted: colon adenocarcinoma (5 papers); heart failure (3); hydatidiform mole (3); multiple myeloma (3); Bardet-Biedl syndrome (2); clear cell renal cell carcinoma (2); congenital diaphragmatic hernia (2); craniopharyngioma (2); cutaneous T-cell lymphoma (2); Down syndrome (2); ductal carcinoma in situ (2); Encephalopathy (2); ependymoma (2); fibrosis (2); hematological disorders (2); hypogonadism (2); Klinefelter syndrome (2); mucinous adenocarcinoma (2); myelogenous leukemia (2); neurodevelopmental disorder (2); neuroectodermal tumors (2); oropharyngeal tumor (2); polydactyly (2); prostate (2); sinonasal undifferentiated carcinoma (2); upper tract urothelial carcinoma (2); adenomatoid odontogenic tumor (1); amblyopia (1); ampullary carcinoma (1); amyloid (1).
A further 134 diseases each share a sentence with SOX2 in 1 paper.